CHRNA7 (cholinergic receptor nicotinic alpha 7 subunit)
Diseases named in the same sentence as CHRNA7 in open-access papers (continued):
Sharing a sentence is not in itself a finding about the gene and the disease.
tumor (continued). "Our findings demonstrate that pharmacologic activation of CHRNA7 reduced tumor progression and improved survival, which led us to explore its effects across multiple models including the E0771 model, the highly aggressive and metastatic 4T1 TNBC model, and the spontaneous multifocal MMTV-PyMT model." (PMID 40653990, 2025). "Our results are consistent with the hypothesis that CHRNA7 action is dependent on APCs through an alternate pathway, ultimately reducing tumor growth and increasing survival." (PMID 40653990, 2025). "Together, these observations supported a functional role for CHRNA7 in mediating tumor progression, which along with increased CHRNA7 expression in myeloid immune cells, suggesting that CHRNA7 may be a novel therapeutic target." (PMID 40653990, 2025). "Apparently, infiltrating immune cells might compensate for this drop much more efficiently than tumor cells, thus explaining the more robust maintenance of CHRNA7 expression in CP compared to PDAC tissues." (PMID 29545933, 2018). "Results of in vitro studies implied that SLURP1high-patients might be better protected against PDAC recurrence or progression through direct anti-malignant effects of SLURP1 on CHRNA7-positive tumor cells." (PMID 29545933, 2018). "With in vitro data supporting a functional role for CHRNA7 activity in immune cell activation, and the tumor permissive phenotype of CHRNA7KO mice, we performed a combination of immunohistochemistry and flow cytometry to localize and quantify tumor-associated immune cells." (PMID 40653990, 2025). "Together, the identification of CHRNA7-regulated chemokines (i.e. NanoString array) and genes (i.e. scRNAseq) established candidate molecular endpoints to better define the role(s) of CHRNA7 in specific myeloid immune cell types involved in adaptive immune responses relevant in tumor progression." (PMID 40653990, 2025). "In particular, the expression of the CHRM1, CHRNA2, CHRNA4, CHRNA6, CHRNA7, and CHRNB2 genes was increased in samples from the tissue of the anterior edge of the tumor." (PMID 38393158, 2024). "Based on CHRNA7 expression in monocytes, macrophages, and DCs, we focused on immune competent mouse models of TNBC to determine the functional role of CHRNA7 in mediating immune cell activation in tumor progression." (PMID 40653990, 2025). "While the expression of many AChRs was not altered in comparison to the cellular tumor, we did find significant upregulations in the expression of CHRNA7, CHRNB2, CHRM1, and CHRM3 in these areas." (PMID 31590360, 2019). "Most probably, the direct anti-malignant effect of SLURP1 on PDAC cells is not the only mechanism behind SLURP1-driven oncosuppression: tumor cells were not a sole source of the pancreatic CHRNA7 expression in cancerous lesions." (PMID 29545933, 2018). "Pancreatic tissue was not a source of circulating SLURP1 but contained diverse CHRNA7-expressing cells, preferentially epithelial and immune, whereas stromal stellate cells and a quarter of the tumor cells lacked CHRNA7." (PMID 29545933, 2018). "Based on genetic approaches establishing a tumor-permissive phenotype using CHRNA7KO mice, we next tested a pharmacological approach that focused on in vivo testing of a small molecule agonist that is highly specific for CHRNA7, AR-R17779, in several different models of TNBC." (PMID 40653990, 2025). "Notably, CHRNA7-immunopositivity of the tumor cells not only lacked own prognostic relevance but also did not correlate with the total CHRNA7 mRNA content in the PDAC lesions (Rho = 0.091; p = 0.580)." (PMID 29545933, 2018). "Moreover, CHRNA7 signaling may directly activate PI3kinase, MAP-kinase, and NF-kB pathways, known promoters of tumor angiogenesis and proliferation." (PMID 29545933, 2018). "This is consistent with our IHC findings, where tumor infiltrations had higher CHRNA5 levels than tumor islands, which was not the case for CHRNA3 and CHRNA7." (PMID 41201200, 2025).
tumor (continued). "The transcriptomes (scRNA‐seq) of 2215 tumor cells from 18 HNC patients were analyzed, in which CHRNA5‐dominant cells were the most (47%), followed by the cells lacking expression of CHRNA3, CHRNA5, and CHRNA7 (41%)." (PMID 41201200, 2025).
psychiatric disorder (8 papers, 2011 to 2024). A disorder characterized by behavioral and/or psychological abnormalities, often accompanied by physical symptoms. "The CHRFAM7A and CHRNA7 genes that reside in the BP4–BP5 region have been linked to psychiatric disorders." (PMID 23320815, 2013). "The 15q13.3 microdeletion syndrome is a genetic disorder characterized by a wide spectrum of psychiatric disorders that is caused by the deletion of a region containing 7 genes on chromosome 15 (MTMR10, FAN1, TRPM1, MIR211, KLF13, OTUD7A, and CHRNA7)." (PMID 33785025, 2021).
infection (5 papers, 2014 to 2025). The state of being infected such as from the introduction of a foreign agent such as serum, vaccine, antigenic substance or organism. "Our findings build upon studies of CHRNA7KO mice in models of infection and injury in which the loss of CHRNA7 leads to unattenuated inflammatory responses that have been primarily attributed to macrophages." (PMID 40653990, 2025). "At 24-week post infection, the AD genes Chrna7, Vnsl1, and MAPK were upregulated, and they play significant roles in the homeostatic function of neurons." (PMID 40171450, 2025). "The functional role for CHRNA7 in monocytes, macrophages, and to a lesser degree, antigen-presenting cells (APCs) has been established in many studies in models of injury and infection." (PMID 40653990, 2025). "In cells where infection with CRE particles abolished Chrna7 expression, the KET-induced CREB activation remained unchanged, but effect of HNK was completely abolished (CTRL-CRE:0.97 ± 0.04; KET-CRE:1.34 ± 0.03; HNK-CRE: 1.0 ± 0.03)." (PMID 38253622, 2024). "The concept that CHRNA7 functions in immune cells to modulate anti-inflammatory signaling and transcriptional reprogramming of immune cells has been further studied in adoptive transfer studies of injury and infection." (PMID 40653990, 2025). "We were also able to drive expression of GCaMP in AON-OB projection neurons via retrograde infection with the same virus after injection into the OB of young (postnatal day 1–3) (7 mice) or adult Chrna7-Cre (2 mice) animals, as previously reported for cholecystokinin (CCK)-expressing neurons in AON." (PMID 25071454, 2014).
neurodevelopmental disorder (5 papers, 2018 to 2024). A behavioral and cognitive disorder with onset during the developmental period that involves impaired or aberrant development of intellectual, motor, or social functions. "In particular, the CHRNA7 gene is listed as a strong candidate in the SFARI database with a score of 2.1, making it an important candidate gene for neurodevelopmental disorders." (PMID 38674362, 2024).
neurological diseases (2 papers, 2022). "In this review, we will outline the current state of hiPSCs technology applications in neurological diseases caused by CNVs in CHRNA7 gene." (PMID 36684422, 2022).
bacterial infection (1 paper, 2017). "Another important question is why neutrophils and monocytes accumulated in the vagotomized and Chrna7−/−Itgam−/− lungs but did not reduce bacterial infection." (PMID 28529765, 2017).
CHRNA7 also shares sentences with these, for which no sentence is quoted: Parkinson disease (4 papers); attention deficit-hyperactivity disorder (3); colitis (3); colon carcinoma (3); neuroblastoma (2); neurodegenerative disease (2); psychosis (2); arrhythmogenic right ventricular cardiomyopathy (1); Arthritis (1); asthma (1); atherosclerosis (1); autoimmune hemolytic anemia (1); autoimmune pancreatitis (1); autosomal dominant nocturnal frontal lobe epilepsy (1); behavioral disorders (1); cardiac hypertrophy (1); cervix cancer (1); cognitive disorder (1); COVID-19 (1); diabetes (1); dyspraxia (1); encephalitis (1); epidermoid carcinoma (1); esophageal squamous cell carcinoma (1); food allergy (1); generalized anxiety disorder (1); genetic disorder (1); head and neck cancer (1); heart failure (1); hepatocellular carcinoma (1).
A further 23 diseases each share a sentence with CHRNA7 in 1 paper.